TNF (tumor necrosis factor)
Diseases named in the same sentence as TNF in open-access papers (continued):
Sharing a sentence is not in itself a finding about the gene and the disease.
infection (continued). "Noticeably, PC1 mostly segregated the non-infected vs. infected populations and PC2 distinguished the infection parameters (infection index, percentage of infection, oxidative burst, Elastase, and MPO) vs. the cytokines IL-6, IL-10, IL1-β, and TNF-α production." (PMID 31134162, 2019). "G-1-treated female mice also had reduced levels of the inflammatory cytokine TNFα at the site of infection, with no significant reduction in levels of the other cytokines tested or MPO compared to vehicle-treated mice." (PMID 30718654, 2019). "Additionally, after infection, the IDR, the levels of TNF-α secreted into supernatants and the frequencies of CD8+IFN-γ+- secreting T cells were good correlates of protection." (PMID 31024556, 2019). "In brief, induction of organ homogenate cytokine production was low or not increased in response to infection (tumor necrosis factor alpha [TNF-α] and IFN-γ), except for interleukin 1β (IL-1β), which largely reflected organ bacterial loads." (PMID 31822597, 2019). "Anti-TNF therapy slightly but not significantly increases the incidence of infection in JIA children compared to other therapies (GRADE: moderate evidence)." (PMID 30658717, 2019). "In the presence of an infectious agent, leucocytes and epithelial cells produce chemoatractants, cytokines (e.g., IL-8, IL-1, TNF-α) and acute phase proteins (e.g., haptoglobin [Hp], serum amyloid A [SAA]), that attract neutrophils to the site of the infection." (PMID 31417901, 2019). "The expression density of IFN-γ on splenic ILC1s was not affected by infection, whereas an enhanced expression density of TNF-α was observed." (PMID 29623077, 2018). "Levels of type I IFNs, TNF-α, IL-6 and CXCL1 as well as CCL2, and IFN-γ were all significantly higher in lungs of 6:2 Tky/05 virus infected mice than in the other three groups at day 2 post infection." (PMID 29300777, 2018). "We found that Mll5−/− PMs had higher gene expression and protein secretion of IFN-β, TNF-α, and IL-6 than their wild-type counterparts had in response to infection with VSV or SeV, but not HSV-1." (PMID 29593341, 2018). "IL-6, CXCL10 and TNF-α concentrations were undetectable in many of the animals regardless of infection status." (PMID 29391069, 2018). "Also, and as detected after stimulation with NH36, the frequencies of CD4+TNF-α+ and CD4+TNF-α+IFN-α T cells were still higher in infected controls and only increased by the F3-vaccine, on day 28 after infection." (PMID 29867949, 2018). "We note that TNFα, IL-6 and IL-10 are induced also by HSV, so their presence may in part be consequent to infection." (PMID 30080893, 2018). "Taken together, we show that in the absence of TNF an infection with L. major BNI quickly spreads to the liver." (PMID 29403488, 2018). "Most studies have found that the presence of BT in cirrhotic patients is associated with significant hemodynamic changes, even in the absence of clinical infection, and is due to the release of inflammatory mediators like tumor necrosis factor-α (TNF-α)." (PMID 29699477, 2018). "The greater production of TNF in response to AF2122 infection was also observed at the protein level, which was statistically significantly different from that produced in response to G18 infection over the 72-h time course (P < 0.001)." (PMID 29263113, 2018). "TNF in the serum was not significantly different by 24 h post-infection, as compared to primary challenge with Lm-gp61." (PMID 29438281, 2018). "Infection of DCs by dengue virus, though, leads to cell maturation and production of TNF-α and interferon (IFN)-α, but not IL-6 and IL-1218." (PMID 30401896, 2018). "Both RGV and ADRV infection induced the up-regulation of cytokines at 1 dpi, such as IL6, IL8, TNFα, and CD114, which could benefit the neutrophil formation and proinflammatory and chemotactic effects." (PMID 29558886, 2018).
infection (continued). "Considering the importance of bacterial colonization and its products on macrophage activation and TNF-α production, as described by several authors, it can be suggested that the presence of infection is not the limiting factor of the healing." (PMID 29592858, 2018). "Given the role of TNF-α on both the innate and adaptive immunity, it is not surprising that the major toxicity concern with the anti-TNF-α agents is the risk of serious infection." (PMID 30060508, 2018). "Neither the infection of human DC and MP nor their stimulation with inactivated virus induced the production of TNF-α, IL-1β, IL-2, IL-6, IL-8, IL-10, IL-12p35, TGF- β, IFN-γ, or CD25." (PMID 30373278, 2018). "However, although P. vivax and P. falciparum malaria patients have similar cytokine profiles during infection, P. falciparum patients presented higher levels of IFN‐γ, TNF‐α, and IL‐2 in acute phase than P. vivax." (PMID 29314720, 2018). "In the multivariate analyses, the hazards of serious infection for DMARDs, TNFi, and tofacitinib were not significant different compared with non-TNF biologic." (PMID 29566769, 2018). "A previous study using mice showed that after infection there is an increase in CD4+ T cells, interferon-γ, tumor necrosis factor-α and inducible nitric oxide synthetase that mediate the development of ileus necrosis and subsequently lead to the death of the mice in 13 days." (PMID 29324806, 2018). "PC were isolated from mice 8 weeks after infection and cultured in the presence of either prostratin and SAHA, the most efficient inducers of latent EcoHIV in CD4+ cells, or TNF-α, an inflammatory cytokine that induces HIV expression in transformed human macrophages." (PMID 29879225, 2018). "The association of TAK1 with the proteins was not affected within 40 min of infection with H. pylori or 10 min of stimulation with TNF or IL-1β." (PMID 29581850, 2018). "Considering that VPA induced a decrease in the production of TNF-alpha and IL-6 in DENV-2-infected PBMCs, we evaluated the effect of this drug on a primary culture of human monocyte-derived macrophages treated 3 h before or after infection with DENV-2." (PMID 29986388, 2018). "25-HC improved the overall IFN-γ-producing cellular responses which are beneficial for controlling HIV-1 replication, but selectively suppressed IL-2/TNF-α-producing proinflammatory CD4+ T cells which are helpful for reducing inflammation and infection targets of HIV-1." (PMID 30524435, 2018). "Furthermore, MSCs can inhibit protein production and gene expression of tumor necrosis factor-α (TNF-α), which plays a critical role in protection against many infections." (PMID 30428931, 2018). "Levels of TNF-α were not altered by N315 αHL+ infection in either non-diabetic (CN315) or diabetic (DN315) animals." (PMID 30705678, 2018). "In our study, we did not observe a detectable level of TNF-α from the serum of our patients collected from the first two weeks of infection." (PMID 29651328, 2018). "We report a strong induction of numerous pro-inflammatory cytokines, chemokines and AMPs such as CXCL1, CXCL2, CXCL5, CXCL8, CCL20, TNFα, TSLP, IL-23α, IL-32, IL-6, hBD2 and S100A7 during the infection of monolayered primary keratinocytes and reconstructed epidermis with the wild-type PAK strain." (PMID 30070169, 2018). "VIP (10 nM) alleviated the NO2- generation induced by IFNγ and TNFα with and without infection (p<0.001)." (PMID 30252907, 2018). "Similarly, infection of THP-1 cells with WT F. tularensis induced a rapid and robust induction of TNF-α." (PMID 29311235, 2018). "The elimination of MyD88 in cardiomyocytes determined a lower increase in CCL5, IFNγ and TNFα gene transcription during acute infection by T. cruzi parasites of the Y strain, but it did not significantly modify heart leukocyte infiltration and parasitism." (PMID 30067739, 2018).
infection (continued). "MG groups had higher levels of TNF-α, IL-1B, and IL-6 compared to no-infection groups (both miR-451-M and miR-451-Inh), as a result of the higher gga-miR-451 expression in the MG group." (PMID 29652844, 2018). "Since, epithelial cells were shown to be the source of pro-inflammatory cytokines like TNF-α and IL1-β after infection with M. bovis, these cell death routes could be of importance for infected epithelial cells." (PMID 30280094, 2018). "Though the source of infection was never clearly identified from multiple imaging studies, we suspect the severity of her presentation was due to her history of TNF-antagonist use." (PMID 29951326, 2018). "RT-qPCR analysis of the expression of key components of the host innate immune response to infection, such as the chemokines/cytokines CCL20, CXCL8, TNF-α, the two β-defensins, LAP and TAP and the acute phase protein SAA3, confirmed the different abilities of R- and S-LPS to stimulate PS cells." (PMID 30142177, 2018). "In our study, we observed an increase in hepatic monocyte/macrophages during SIV infection that correlated with both inflammatory (TNFα, CCL3) and fibrosis (TGFβ) mediators suggesting multiple, and maybe even opposing, roles during infection." (PMID 29466439, 2018). "Through the first four days of infection and co-treatment with eritoran, viral titers did not notably decrease; however, pro-inflammatory cytokines and chemokines, such as TNF-α, IL-1β, IL-6, and CXCL1 were mitigated during this early infection and the IAV infection resolved more rapidly." (PMID 29988424, 2018). "Interestingly, even in this analysis, levels of IFNγ, TNFα, IP-10, sCD163 and CRP in Group 4 became comparable to those of Group 5, which initiated ART one week post-infection (p = ns)." (PMID 30161247, 2018). "In addition, inhibition of PLC with D609 reduced production of inflammatory mediators, including TNF-α, IL-10, and NO, in LPC-treated cells during H37Ra infection." (PMID 29755479, 2018). "Our study supports the hypothesis of a Notch-transduced amplification of inflammation during infection as it reveals a gain of TLR4-primed and NF-κB -mediated expression of IL-6 and TNFα through Notch activation." (PMID 30042932, 2018). "Infection of DCs with Rift Valley Fever virus (RVFV) induces the expression of TNF-α, IL-6, and IL-10 but not IL-8, IL-19, or IL-1β17." (PMID 30401896, 2018). "Taken together, these findings indicate that the absence of TNF results in defective antiviral innate immune activation after infection with VSV." (PMID 29142134, 2018). "In patients with RA previously treated with methotrexate, our comparisons of tofacitinib with non-TNF biologics, though not definitive, did not demonstrate differences with respect to hospitalized infections or effectiveness." (PMID 29566769, 2018). "At lower infection doses, significant differences in height and kinetics of cytokine concentrations in BAL-f were mostly confined to the time point around the maximum cytokine response (2–4 h for IL-1β and Ccl3, 2–8 h for TNF, 8–24 h for Cxcl-1, Ccl2)." (PMID 29734720, 2018). "The results indicated that IL-6, IL-10, TNF-α, TGF-β, and iNOS expression in the infection group was significantly higher than in the control group, an increase of 1.2-fold, 0.29-fold, 0.32-fold, 0.12-fold, and 3.95-fold, respectively, as well as an increase of CD86 (P = .891) and CD206 (P = .303)." (PMID 30170447, 2018). "The role of CD8 T cells during infection for protection has been also recently investigated, with CD8 T cells that produce IFN-γ and TNF-α enhancing cytolytic activity and secreting IL-2 to promote cell expansion that could enhance CD8 T cell memory function." (PMID 30631322, 2018).
infection (continued). "The increase in the gene expression of IFN-γ, TNF-α, IL1-β, and iNOS in the liver of both groups after the infection is indicative of a systemic dissemination of S. Typhimurium which stimulated the hepatic macrophages to produce these pro-inflammatory cytokines." (PMID 30564201, 2018). "IL-1α and TNF-α are also more abundant in the lungs of C57BL/6J mice, suggesting that wild-type but not C3–/– mice develop a fever response to infection that contributes to weight loss and respiratory dysfunction phenotypes." (PMID 30301856, 2018). "“Sterile” chronic, low-grade inflammation without any obvious infection is a common feature of ageing, and people over the age of 65 have increased serum levels of IL-6, TNF, and IL-1855,56." (PMID 29426925, 2018). "The suppression of TNF signaling by Tnf siRNA treatment was seen to markedly increase bacterial survival during late infection without affecting bacterial internalization." (PMID 30186773, 2018). "Indeed, we found the proinflammatory cytokines IL-1β, TNF, and Ccl3 reduced in BAL-f of ExoY-infected mice as compared to ExoYK81M-infected mice at 2–4 h after infection." (PMID 29734720, 2018). "The situation in different during M. tuberculosis infection in which T cell-derived TNF is needed to control the infection and can better not be blocked, whereas myeloid cell-derived TNF is dispensable." (PMID 29751683, 2018). "The fact that the response was shortly activated at the site of infection argues for the presence of effector memory T cells as this cell population is known to counteract re-infection by secreting anti-microbial cytokines such as IFN-γ and TNF-α." (PMID 29892298, 2018). "By using combinations of EP2 and EP4 receptor agonists/antagonists, we showed that while EP2 receptor signaling plays a significant role in regulating TNF-α levels, EP4 receptor stimulation seemed to be the most relevant in the PGE2-mediated secretion of IL-1β upon infection with S. Typhimurium." (PMID 30429830, 2018). "Similarly the mRNAs for TNF-α and cytokines were suppressed in the supernatant of RAW cells infected with the 3 poxviruses at the same infection time point." (PMID 30563103, 2018). "The M2e5x VLP group showed a low level of vaccine-induced pre-existing antigen-specific TNF-α+ and IFN-γ+ CD4 T cells resident in the lung tissues and BAL before infection, which can secrete cytokines upon stimulation and rapidly expand during challenge infection." (PMID 29324805, 2018). "Concerning the impact of FM on the host immunity against Mtb, it was shown that human macrophages exposed to lipids prior to Mtb infection failed to produce TNF-α and to clear the infection." (PMID 29593722, 2018). "TNF-α was found to be generally high in children aged between 11 and 12 years irrespective of their infection status." (PMID 29970128, 2018). "While we did not observe significant differences in expression of IFNγ, TNF or IL-6, as compared to macrophages isolated after primary Lm-gp61 infection, heterologous challenge resulted in a significant induction in IL-12p35 expression by splenic macrophages." (PMID 29438281, 2018). "Non-activated human macrophages respond to infection with Salmonella by secreting cytokines such as TNF-α, IL-12, and chemokines including IL-8 (CXCL8)." (PMID 29538403, 2018). "TNF-α expression was similar in all groups, and surgery or infection did not induce gender-related differences except in the sham-infected groups; males exhibited higher TNF-α mRNA expression compared to that in females in the same condition (P < 0.001)." (PMID 30515051, 2018). "Tumor necrosis factor alpha (TNF-α) and IL-1 induce endothelial adhesion molecules, which trigger the migration of innate immune cells, such as macrophages, blood borne DCs, and natural killer (NK) cells to the site of infection." (PMID 29556226, 2018).
infection (continued). "Insulin treatment did not induce increased cytokine production against the infection in diabetic mice, although mice from both the control group and the diabetic group infected by Pb18 showed increased production of TNF-α after insulin treatment." (PMID 30426021, 2018). "Our results suggest that LDA does indeed balance TNF-α in TB in C3HeB/FeJ mice, significantly increasing serum levels in earlier stages (week 3) and reducing serum levels in the later stages of infection compared to non-treated positive controls." (PMID 29740435, 2018). "Our data suggested that NOD2 activity began to increase in brain tissue 12 h after infection, while those of IL-1β, TNF-α, and IL-6 showed no obvious changes at 12 h." (PMID 30186539, 2018). "On the 28th day of infection and 23 days of treatment, the euthanasia occurred, and the heart preserved for histopathological, oxidative stress (SOD, catalase, TBARs, carbonylated proteins) and plasma (CCL2, CCL5, TNF, IL-10) analyses." (PMID 30365644, 2018). "TNFα−/− mice were infected with M. tuberculosis H37Rv, treated with INH and RIF from day 14 to 32 post-infection and received either anti GM-CSF MAB or IgG2b isotype control on day 14 and 21 post-infection (200 ug i.p.)." (PMID 29872095, 2018). "However, when exogenous stimulation is applied via LPS even 8 days after infection with HBV, KC rapidly secrete IL-6 and TNF-α." (PMID 29445209, 2018). "As expected, ECTVΔCrmD-infected cell supernatants showed neither expression of CrmD protein nor TNF blocking activity, whereas infections with either parental or revertant viruses showed similar levels of CrmD and TNF inhibitory activity." (PMID 29724993, 2018). "Similar to airway epithelial cells, human macrophages express type I and type III IFNs, IL-1α, IL-1β, IL-6, TNF-α, CXCL8, CCL2 (MCP-1), CCL3 (MIP-1α), CCL4 (MIP1-β), CXCL9, and CXCL10 following infection with seasonal H1N1 or with H5N1, 2009 H1N1 strains demonstrating increased pathogenicity." (PMID 29623073, 2018). "In addition, the levels of TNF-α in the BAL and lungs from naïve mice were higher than those in immune mice day 3 and 6 post infection." (PMID 29324805, 2018). "During infection, an initial proinflammatory Th1-type polarized response is continuously triggered by schistosome-soluble adult worm antigen fractions, with elevated interferon-γ (IFN-γ), tumor necrosis factor-α (TNF-α), and interleukin-12 (IL-12) levels." (PMID 30116754, 2018). "Activated immune cells induce Fas-L and upregulate Fas, TNF and TRAIL to induce apoptosis in the cells; and infection of HIV-1 can further exaggerate hepatocytes death by triggering TLR-mediated innate immune response and by elevated proinflammatory cytokines in the liver-immune cell milieu." (PMID 29361613, 2018). "Infection of MoDCs by L. braziliensis in non-stimulated cultures increased levels of TNF, IL-12p40, and IFN-γ compared to uninfected cultures (respectively)." (PMID 30687325, 2018). "Therefore, blockading the generation of TNF-α with varied neutralizing antibodies is indicated to be an effective remedy for IBD, although the side effects, which include serious infection, remain a major concern." (PMID 29880739, 2018). "At the same time, indicators of inflammatory response such as production of IFN-γ, TNF-α, IL-1β, and IL-6 mediated by TLR/MyD88/NFκB were also activated after N67 infection, which may explain the pathology and host death later in infection." (PMID 30327482, 2018). "3D PHH cultures themselves do not produce any IL-6 and TNF-α in response to infection with HBV since these cytokines are KC specific." (PMID 29445209, 2018). "Prior to infection, 26.6 ± 11.8% and 24.4 ± 3.2% of the γδ T cells in the spleen could produce IFN-γ and TNF-α, respectively." (PMID 30619302, 2018).